CST9LP1 (cystatin 9-like pseudogene 1)
Synonyms: CTES7C
Gene: Transcribed unprocessed pseudogene on chromosome 20 (23,547,764 to 23,550,652, reverse strand). Ensembl gene ENSG00000204662.
Subcellular location: Secreted